APP (amyloid beta precursor protein)
Diseases named in the same sentence as APP in open-access papers (continued):
Sharing a sentence is not in itself a finding about the gene and the disease.
Parkinson disease (continued). "We also reported rare heterozygous variants in neurodegenerative disease related genes, including TRPM7, MAPT, and APP that could be associated with parkinsonism phenotypes; however, none have been previously reported as pathogenic." (PMID 39867380, 2025). "In addition to neurons, arsenic increases proinflammatory cytokine levels in astrocytes, a type of glial cell, potentially leading to elevated levels of amyloid precursor protein (APP) and subsequent α-synuclein aggregation, known as a molecular signature of Parkinson’s disease." (PMID 38928831, 2024). "It is well known that the toxic amyloid-like aggregates of β-amyloid (APP), tau (MAPT), α-synuclein (SNCA or PARK1), and islet amyloid polypeptide (IAPP) are linked with neurodegeneration in Alzheimer’s disease (AD), frontotemporal dementia (FTD), Parkinson’s disease (PD) or Type 2 diabetes (T2D)." (PMID 35565658, 2022). "In addition, considering a recent report describing a putative IRE in the 5'UTR of Parkinson's disease related α-synuclein mRNA, a parallel can be drawn between APP and α-synuclein both in the physiological and pathological aspects with respect to iron regulation." (PMID 19090990, 2008). "In the NHP CSF, 983 proteins were identified by at least two unique peptides, including proteins with key roles in neurological diseases, such as APP, TREM2 and ApoE in AD, DJ-1/PARK7 in Parkinson’s disease and the prion protein in prion diseases." (PMID 36810097, 2023). "(Aβ= amyloid beta; APP= amyloid precursor protein; DJ1= Parkinson’s disease (autosomal recessive, early onset) 1; PINK1= phosphatase and tensin induced putative kinase 1; SOD1= superoxide dismutase 1)." (PMID 20938400, 2010). "Studies have demonstrated that individuals carrying specific genes exhibit significantly elevated risks of developing NDDs: for instance, the APP gene carried by patients with AD, and the α-synuclein (SNCA) gene carried by patients with Parkinson’s diseases (PD)." (PMID 40430516, 2025). "There are protein aggregates, known as lewy bodies, containing α-sinculein (αS)—non-amyloid component of APP—and ubiquitin, in the midbrain of Parkinson’s patients." (PMID 28651647, 2017). "Besides being major contributors of neurodegeneration process, APP, CREB1, HSP90AA1, MAPT and PTEN have varying degree of interactions with many known Parkinson's disease genes (see CSPNW)." (PMID 24688734, 2013). "Therefore, our selection of biomarkers encompassed those previously validated by our research group, along with common biomarkers identified within the proteome array present in the peripheral blood of APP/PS1 mice, a standard model for AD, and the MPTP-induced Parkinson’s disease (PD) model." (PMID 39170638, 2024). "Mouse (M. musculus) — 0.5 mg/kg (once a day, orally) improved short-term memory in an Alzheimer's mouse model (APP/PS1 double mutant mice).Also, DNP protects against motor dysfunction (1 or 5 mg/kg) and dopaminergic neuronal injury (5 mg/kg) induced by MPTP (a Parkinson's disease model in mice)." (PMID 37650304, 2023).
diabetes (63 papers, 2009 to 2025). "Diabetes-linked inflammation triggers neuronal C/EBPβ activation, leading to increased APP and Tau expression." (PMID 40977745, 2025). "While a direct causal link between diabetes-induced APP dysregulation and HNSCC remains to be elucidated, the convergence of metabolic and oncogenic functions suggests a plausible mechanistic bridge." (PMID 40881172, 2025). "The current diabetes model was linked to elevated APP and BACE expression as well as reduced PSEN2 expression." (PMID 38683825, 2024). "Dysregulated proteolysis of RAGE and APP in type 2 diabetes mellitus also provides a possible risk factor to AD." (PMID 36845656, 2023). "Pathological features of AD, including tau phosphorylation and amyloid plaque deposition, were exaggerated in the brains of APP transgenic mice following the induction of insulin-deficient diabetes." (PMID 28422052, 2017). "Patients with diabetes mellitus (DM), characterized by chronic hyperglycemia,have increased risk of AD development.However, the role of high blood glucose in APP processing and Aβ generation remains elusive." (PMID 23894546, 2013). "To understand the mechanism whereby diabetes increases the risk of AD, we generated AD model mice with a diabetic phenotype by crossbreeding APP Tg mice and leptin-deficient ob/ob mice." (PMID 24204343, 2013). "In this study, we applied streptozotocin (STZ) to induce experimental diabetes in AD transgenic mice (5XFAD model) and investigated how insulin deficiency affects the β-amyloidogenic processing of amyloid precursor protein (APP)." (PMID 22403710, 2012). "Consistent with previous reports, our findings showed that insulin deficient diabetes induced by STZ exacerbated the accumulation of Aβ in APP/PS1 transgenic mice." (PMID 21044348, 2010). "In the present study, a mouse model of combined insulin-deficient diabetes and AD was made by injecting APP/PS1 transgenic mice with STZ, a known toxin for pancreatic insulin-producing β-cells." (PMID 21044348, 2010). "Tobacco smoking and diabetes, both of which are associated with hypoxia, have also been shown to be associated with substantial changes in the transcription of AD associated genes, for example, APP and MAPT." (PMID 35852137, 2022). "Diabetes may predispose individuals to AD, as demonstrated in the APP/PS1 mice model of AD." (PMID 38539672, 2024). "To more fully elucidate neuroinflammatory changes associated with diabetes that may drive AD pathology, we combined the APP/PS1 mouse model with either high-fat diet (HFD, a model of pre-diabetes), the genetic db/db model of type 2 diabetes, or the streptozotocin (STZ) model of type 1 diabetes." (PMID 31992349, 2020). "First, APP mice with the hypertensive db/db background show increased phospho- tau levels, but increased Aβ and neuroinflammation associated with diabetes in this model could have driven tau hyperphosphorylation independent of hypertension." (PMID 31708792, 2019). "Taken together, our findings provide a mechanistic foundation for a link between diabetes and AD by demonstrating that insulin deficiency may change APP processing to favor β-amyloidogenesis via the translational upregulation of BACE1 in combination with elevations in its substrate, APP." (PMID 22403710, 2012). "Transgenic mice expressing both human amylin and APP exhibited exacerbated AD-like pathology compared with mice expressing human APP only or expressing human APP with streptozotocin-induced type 1 diabetes mellitus (T1DM) background." (PMID 37895336, 2023). "A study discovered an increased amyloid precursor protein (APP) load, in addition to a decreased insulin receptor activity in the brain of diabetes-induced (via intraperitoneal administration of streptozotocin) AD-transgenic hAPP (human-APP) mice." (PMID 33218163, 2020).
diabetes (continued). "As compared to AD mice, the phosphorylation levels of tau were increased in the offspring mouse model of diabetes and AD hybridization (Pdx1+/–/APP/PS1); furthermore, the production of Aβ was increased and the clearance of Aβ was inhibited." (PMID 32774301, 2020). "Since diabetes also affects vascular integrity and blood-brain barrier, it is feasible that the increased spontaneous central bleeding observed in APP/PS1xdb/db mice is related, at least in part, to GM-CSF-glucose association." (PMID 31992349, 2020). "A rodent model of diabetes exhibits AD-related alterations such as increases in APP, amyloid-β, and phosphorylated tau." (PMID 31461911, 2019). "Along with these prior works, we developed an animal model that exhibited both diabetes and AD by crossing APP/PS1 and ob/ob mice." (PMID 28467789, 2017). "The ROS production in the brains of mice with diabetes was significantly higher than in the WT and APP/PS1 mice (p < 0.05)." (PMID 28467789, 2017). "BBr strongly reduced the expression level of APP which was induced by diabetes, and Met had the same effects." (PMID 28634451, 2017). "Here, we developed an animal model that exhibited both diabetes and AD by crossing APP/PS1 and Pdx1+/− mice." (PMID 27406855, 2016). "In order to further study this relationship, we have induced hypoinsulinemic diabetes to APPswe/PS1dE9 (APP/PS1) mice, a classical model of AD." (PMID 26156287, 2016). "Consistently, here we found that the FDA approved anti-diabetes drug pioglitazone can inhibit Cdk5 activity in both hippocampal neurons and APP/PS1 mutant mouse hippocampi." (PMID 25875370, 2015). "The neuronal firing pattern in the hippocampus was changed in STZ-diabetic rats and APP 17-mer peptide partially reversed the effect of diabetes mellitus." (PMID 25093193, 2014). "It has been reported that APP 17-mer peptide is an effective therapy for diabetes-induced impairment of cognition." (PMID 25093193, 2014). "Consistent with these clinical observations, we found that AD aggravated the diabetic phenotype in two different lines of APP Tg mice with diabetes." (PMID 24204343, 2013). "Previous report has shown that people with diabetes have higher APP level in platelets than controls." (PMID 23894546, 2013). "Hence, the high eNOS protein levels in APP mice may reflect a compensatory upregulation in response to the reduced NO bioavailability following its trapping by reactive oxygen species, as also reported in a model of diabetes-associated vascular disease." (PMID 23642031, 2013). "In conclusion, the results presented here demonstrate that STZ-induced insulin-deficient diabetes exacerbates Aβ accumulation by elevating expression levels of the β-secretase enzyme BACE1 and its substrate APP in the 5XFAD mouse model of AD." (PMID 22403710, 2012). "Third, immunoblot analysis showed a significant increase in the C-terminal fragments of amyloid precursor protein (APP-CTFs) in STZ-induced diabetes." (PMID 21044348, 2010). "Diabetes-induced APP expression was significantly decreased by SchA." (PMID 40589410, 2025). "Diabetes positively regulates APP (4 references; q = 0.00015), NLRP3 (19 references; q = 0.00168), and PVT1 (4 references; q = 0.00755), while negatively regulating CYP2C19 (14 references; q = 0.00372), suggesting its influence on pathways related to inflammation, immune response, and metabolism." (PMID 40881172, 2025). "Tissue-specific knockout models for AMPKα1/α2, SIRT1, or PGC-1α can delineate causal roles in immunometabolic remodeling, while disease-specific animal models (e.g., high-fat diet–induced obesity, streptozotocin-induced diabetes, or APP/PS1 Alzheimer’s models) can evaluate physiological relevance." (PMID 41573560, 2025). "The role of APP gene mutations in AD is well-established, but this is not as well-explored in the context of Type 2 Diabetes Mellitus (T2DM)." (PMID 38370359, 2024).
diabetes (continued). "In double-mutant (APP+ -ob/ob) mice, the development of diabetes aggravated AD-like cognitive impairment without causing an increase in brain amyloid-β load." (PMID 38539672, 2024). "Moreover, the amyloid protein (islet APP) generated in the diabetes mellitus pathology in β-cells of pancreas share a structure similarity with neuron APP and, consistently, islet APP fibrillation is prevented by HTyr." (PMID 37049607, 2023). "At the same time, tau and APP expression were also increased, which is similar to the phenotype observed in the AD mouse model, further illustrating the relationship between diabetes and AD." (PMID 32774301, 2020). "To further verify the changes of RAGE in diabetes, we investigated whether there is a link between diabetes and AD by detecting changes in APP and tau in ZDF rats." (PMID 32774301, 2020). "Treatment with APP 17-mer peptide retarded the effects of diabetes on these parameters." (PMID 25093193, 2014). "Although feeding a high-fat diet caused severe memory deficit in APP Tg with NSY background (Nagoya-Shibata-Yasuda) mice, which are established as an inbred animal model with spontaneous development of diabetes, we observed no increase in brain Aβ load by a high-fat diet." (PMID 24204343, 2013). "Moreover, tau phosphorylation is increased in diabetic animals, and mice with combined APP overexpression and diabetes show exacerbated histological features of Alz." (PMID 21533026, 2011). "An in vivo study carried out in mice to connect diabetes mellitus and AD explained that the subjects injected with AGEs demonstrated depleting memory capacity and accumulation of indicators like tau phosphorylation and APP (amyloid precursor protein) antibodies." (PMID 39766986, 2024). "In contemplating this result in the context of the AD/T2D association with SORCS1, this observation raised the possibility that Sorcs1-/- mice crossed with AD model mice (here, APP/PSEN1 mice) might manifest overt diabetes if stressed by the accumulation of cerebral amyloid." (PMID 26916443, 2016). "Furthermore, we revealed that the anti-diabetes drug pioglitazone could suppress Cdk5 hyper-activation in the APP/PS1 mutant mouse hippocampus by decreasing p35 protein level." (PMID 25875370, 2015). "Thus activation of ADAM10-mediated cleavage of RAGE and APP should counteract the development of AD, and furthermore stimulation of RAGE shedding should prevent at least some pro-inflammatory effects associated with diabetes mellitus." (PMID 22860017, 2012). "Thus, metformin attenuates diabetes-induced tau hyperphosphorylation by enhancing autophagic clearance, it reduces tau hyperphosphorylation, attenuating tau pathology and improving learning and memory deficits in the tau-seeded PS19, and attenuates plaque-associated tau pathology in APP/PS1 mice." (PMID 39170185, 2024). "WT and 6-month-old APP/PS1 mice performed equally well, while STZ-induced diabetes significantly impaired the performance of APP/PS1 mice." (PMID 35077394, 2022). "In the present study, we first found that adapentpronitrile significantly ameliorated neuronal injury and decreased amyloid precursor protein (APP) and amyloid beta (Aβ) expression in the hippocampus and cortex in the high fat diet/STZ rat model of diabetes." (PMID 30072873, 2018). "In our study, the APP/PS1 mice were euglycemic and normotensive, excluding potential contribution of diabetes and hypertension to the compromised cardiac function." (PMID 19551139, 2009). "In contrast, there were no significant changes in the level of APP protein in the group treated for two weeks with linagliptin compared to the group of animals with diabetes (p > 0.05)." (PMID 38860903, 2025). "We detected spatial memory alterations in APP/PS1-Sham mice as well as in Wt-STZ-treated mice, and these effects were worsened in APP/PS1-STZ mice, both during the acquisition and retention phases, suggesting a synergistic effect between diabetes and AD." (PMID 26156287, 2016).
diabetes (continued). "Inflammatory process far from plaques was significantly worsened in APP/PS1-STZ-treated mice (F(3,1382) = 42.25, **p = 0.01 vs. the rest of the groups, ‡‡p < 0.01 vs. Wt-Sham), supporting a synergistic effect between diabetes and AD at this level." (PMID 26156287, 2016). "In the present paper, the degree of firing pattern changes in diabetic rats with APP 17-mer peptide treatment was smaller than that in diabetic rats, which implied that treatment of APP 17-mer peptide can retard the degeneration induced by STZ diabetes." (PMID 25093193, 2014). "The consistent directionality and statistical significance observed in the regulation of APP, NLRP3, PVT1, and CYP2C19 suggest the possibility of a Diabetes → gene → HNSCC pathway, in which diabetes-related gene alterations may contribute to HNSCC pathogenesis." (PMID 40881172, 2025). "A recent study in several models of diabetes combined with a classical AD model, such as the APP/PS1 mouse, concludes from the cytokine profiles exhibited in each pathology that neuroinflammation may be the mechanism by which diabetes affects the pathology of AD." (PMID 37873836, 2023). "Given that T2D diabetes, as modeled by db/db and HFD mice, amplified brain Aβ levels and enhanced pro-inflammatory cytokine production, we next hypothesized that peripheral plasma levels would correlate with brain cytokine expression in APP/PS1xdb/db mice." (PMID 31992349, 2020). "Recently, the impact of APP on different human diseases such as neurodevelopmental and neurodegenerative disorders including rare diseases such as autism, FXS, ALS, MS, LND; common and complex disorders such as AD; metabolic disorders such as diabetes; and also cancer has been reported." (PMID 32341983, 2019). "STZ-induced diabetes significantly reduced body weight and glucose tolerance and increased RBG and HbA1c levels, but did not significantly alter blood pressure when compared with APP/PS1 mice." (PMID 35077394, 2022).